COL14A1 (collagen type XIV alpha 1 chain)
Diseases named in the same sentence as COL14A1 in open-access papers (continued):
Sharing a sentence is not in itself a finding about the gene and the disease.
tumor (34 papers, 2009 to 2025). "Among them, the expression of COL1A1, COL10A1 and COL11A1 was particularly higher, and that of COL4A4, COL6A5 and COL14A1 was especially lower in tumor tissues, indicating their possible roles as diagnostic markers for ESCC." (PMID 31598423, 2019). "Notably, tipifarnib treatment increased the number of MyoCAFs, which are often associated with tumor aggressiveness and a dismal prognosis, whereas the control group contained more COL14A1 MatrixCAFs." (PMID 32460812, 2020). "Mutations in other collagens, such as COL6A6, COL22A1, COL6A3, COL12A1, and COL14A1, were also noted in a variety of tumor types." (PMID 34584216, 2021). "Among them, the expression of COL1A1, COL10A1, and COL11A1 were found to be particularly high in tumor tissues compared with normal counterpart; on the contrary, the expression of COL4A4, COL6A5 and COL14A1 was significantly lower in tumor tissues." (PMID 34199373, 2021). "Collectively, these observations point toward an anti-proliferative or tumour suppressor function of COL14A1." (PMID 34095157, 2021). "Five genes (BNC1, COL14A1, CST6, PDLIM4, and SFRP1) demonstrated frequent tumor-specific promoter region methylation (>30%), associated with transcriptional silencing." (PMID 28326264, 2015). "Re-expression of BNC1, CST6, and SFRP1 suppressed the growth of RCC cell lines, whereas RNAi knock-down of BNC1, SFRP1, and COL14A1 increased their growth, suggesting tumor suppressor activity." (PMID 28326264, 2015). "We used methylation specific PCR (MSP) analysis to study DNA methylation status of EPB41L3, GPX3, and COL14A1 genes in tumor and paired surrounding normal tissue from 42 ESCC patients." (PMID 25050929, 2014). "The higher methylation frequency of GPX3 and COL14A1 were correlated with advanced pN tumor stage (P = 0.001 and P<0.001)." (PMID 25050929, 2014). "In our study, we observed that the methylation frequency of COL14A1 was significantly higher in tumor tissues than that in adjacent normal surrounding tissues (P = 0.001)." (PMID 25050929, 2014). "The methylation frequency of EPB41L3, GPX3, and COL14A1 were higher in tumor tissues than in normal surrounding tissues (P<0.017)." (PMID 25050929, 2014). "The MSP analysis revealed that the methylation frequencies of EPB41L3, GPX3, and COL14A1 in ESCC tumor samples were 59.5%, 54.8%, and 45.2%, respectively." (PMID 25050929, 2014). "Interactions via the Cd44/Col14a1 and Cd44/Col1a1 pathways highlight the role of immune cells in monitoring the tumour microenvironment, which may be involved in modulating the inflammatory response and promoting tissue repair." (PMID 40046334, 2025). "myCAFs are located in CAFs adjacent to tumor cells, while iCAFs marked by PDPN and/or COL14A1 are distant from tumor cells, where hypoxic and acidic environments being located in iCAFs putatively due to poor blood supply is consistent with HIF1A and GPR68 expressions." (PMID 38892190, 2024). "Consistently, factor analyses of other lineages revealed overlapping differential gene programs between tumor and injury models, including Treg cell depletion-induced gene programs in Arg1+ macrophages and IC signatures in Col14a1 matrix fibroblasts." (PMID 37127830, 2023). "COL14A1 was highly expressed in 1 tumor and lowly expressed in 15 tumors." (PMID 36936416, 2023). "Notably, in Kitata and colleagues dataset, the protein abundance of COL1A2 and COL14A1 was similar between tumor and normal tissues, while the abundance of the Hyp sites on each of those proteins were well above or below the 95% confidence interval." (PMID 36026437, 2022). "There are, however, significant differences between PTMmut and overall mutations, with e.g., hornerin (HRNR, a paralog of FLG) being a top-10 PTMmut gene in 14/31 tumor types and versican (VCAN), collagen III (COL3A1) and XIV (COL14A1) all mutated in 9/31 tumor types." (PMID 33802493, 2021).
tumor (continued). "Myofibroblasts play a key role in tumor progression, and have been described as cancer-associated fibroblasts, whereas COL14A1+ matrix fibroblasts have been reported in the non-malignant stromal environment." (PMID 34697289, 2021). "COL14A1 interacts with decorin, a small leucine-rich proteoglycan, which has incrementally been shown to be a powerful inhibitor of growth in a wide variety of tumor cells." (PMID 25050929, 2014). "We found that the expression levels of seven integrin ligands (COL4A6, COL13A1, FGB, COL19A1, COL18A1, COL14A1, and COL11A2) were negatively correlated with the Gleason score, suggesting that the suppression of integrins and/or their ligands is associated with more advanced tumor grade." (PMID 19653896, 2009). "Based on the expression of key marker genes-MUC1 (tumor region), LYZ (immune region), COL14A1 (stromal region), and SFTPC (normal region)—we classified the niches into tumor, immune-stromal, and normal regions across all spatial transcriptomic samples." (PMID 40396179, 2025). "Genes such as COL14A1, COL6A1, THBS2, COL4A2 and COL11A1 are involved in tumor migration and invasion." (PMID 37024829, 2023). "For example, C03_PI16 expressed several marker genes, such as COL14A1, CFD, GSN and PI16, similar to the major fibroblast subpopulations in normal tissue and early‐stage tumour in a previous study." (PMID 38115703, 2023). "IHC staining revealed that COL14A1 and TNS1 were over-expressed in peritoneal metastatic lesions relative to primary tumor tissues." (PMID 35515139, 2022). "We then focused on 3 aberrant DNA methylation genes—EPB41L3, GPX3, and COL14A1, with validation analysis using additional ESCC tumor tissues and adjacent normal tissues." (PMID 25050929, 2014). "In addition to the tumor cells (dsRED+), we also found another cell cluster lacking the expression of dsRED that similarly express mesenchymal genes, but which was enriched for additional genes previously associated with CAFs, such as Rarres2, Pi16, Fap, Lum, Sfrp2, Dpt, and Col14a1 5,35." (PMID 38509063, 2024). "The mCAF subset of the tumor stroma specifically expressed transcripts of a large variety of ECM-related genes, such as glycoproteins (Dcn, Lum, and Vcan), structural proteins (Col14a1), matricellular proteins (Fbln1, Fbln2, and Smoc), and matrix-modifying enzymes (Lox and Loxl1)." (PMID 30514914, 2018). "On the other hand, Col4a1, Col4a3, Col4a5, Col5a3, Col11a2, Col14a1, Col15a1, Col16a1, and Col22a1 were found in normal ECM but not in tumor ECM; Col25a1 was found only in tumor ECM but not in normal ECM." (PMID 36547361, 2022).
cancer (19 papers, 2014 to 2024). A tumor composed of atypical neoplastic, often pleomorphic cells that invade other tissues. "On the other hand, miR-324-3p which targets COL14A1, suppresses the invasion and growth of some cancer cells by elevating the apoptosis." (PMID 36978083, 2023). "Forty-eight hours after transfecting siRNA into the cancer cells, a drastic drop in the expression level of COL14A1 and TNS1 was assessed by qRT-PCR." (PMID 35515139, 2022). "This last group included genes involved in cell migration and ECM (e.g. RAB6B, FN1, VCAM1 or COL14A1) and genes of signalling pathways usually deregulated in cancer, such as Notch and Wnt signalling (JAG1 and WNT7B, respectively)." (PMID 34353313, 2021). "A contrary example is, the protein ‘COL14A1’ shows downregulation percentage of 88.9% and upregulation percentage of 11.1% in all cancer types." (PMID 29688359, 2018). "The methylation frequency of EPB41L3, GPX3, and COL14A1 were 31.0%, 40.5% and 31.0% in cancer patients' plasma, respectively." (PMID 25050929, 2014). "In addition, estrogen-induced increased expression of genes related to collagen synthesis, including COL14A1 and COL1A1 in mesenchymal cells, which was associated with cancer cell growth, invasion, metastasis, and angiogenesis." (PMID 39872660, 2024). "The highest expression of genes encoding Col1a1-2, Col3a1, Col4a1, Col4a2, Col5a1, Col5a2, Col6a1, Col8a1, Col9a3, Col10a1, Col12a1, Col14a1, Col15a1, Col16a1, Col18a1, and Col28a1 were detected in untreated tumors, whose landscapes were dominated by Krt8+ cancer cells." (PMID 39372930, 2024). "COL14A1 was significantly downregulated in almost all cancer types." (PMID 36936416, 2023). "COL14A1 is another gene whose role has not been fully understood in cancers." (PMID 36978083, 2023). "Firstly, the biological mechanisms of COL14A1, COL17A1, ITGA10 and MMP7 in IPF and cancer are still unclear." (PMID 36936416, 2023). "It seems that COL14A1 is increased in IPF, while it is decreased in cancer." (PMID 36936416, 2023). "When compared cancer with or without metastasis, it seems that further decrease of COL14A1 has better outcome, but, this has to be tested in a larger scale to validate." (PMID 36936416, 2023). "However, there is a lack of relevant studies to support the effect of COL14A1 on the prognosis of these cancers, and more studies are needed to prove this." (PMID 36936416, 2023). "The differential expression of COL14A1 may indicate the critical signaling that differentiates IPF - a disease with non-stopping fibroblast growth, from cancer-a disease with non-stopping malignant cell growth." (PMID 36936416, 2023).
infection (5 papers, 2023 to 2025). The state of being infected such as from the introduction of a foreign agent such as serum, vaccine, antigenic substance or organism. "However, COL14A1, COLEC11, and COLEC12 were uniquely downregulated following Delta infection at 24 hpi." (PMID 41200555, 2025). "Immunostaining of the dura for COL14A1 did not reveal significant changes one day after infection, likely reflecting the slow turnover of mature extracellular matrix collagen." (PMID 37318981, 2023).
heart (1 paper, 2024). "Of these four key genes, Collagen Type XIV Alpha 1 Chain (COL14A1) has previously been reported to affect arterial remodeling and showed up-regulation mRNA and protein levels in the ischemic heart of HF patients." (PMID 38397416, 2024).
COL14A1 also shares sentences with these, for which no sentence is quoted: 3-M syndrome (1 paper); adenocarcinoma (1); cardiovascular diseases (1); chronic kidney disease (1); clear-cell renal-cell carcinomas (1); connective tissue disorder (1); coronary artery disease (1); COVID-19 (1); endometrial carcinoma (1); endometriosis (1); heart failure (1); Hepatitis (1); hypertrophy (1); idiopathic pulmonary fibrosis (1); immune system disease (1); ischemia (1); kidney cancer (1); metastatic cancer (1); Myocardial fibrosis (1); nephrotic syndrome (1); pancreatic adenocarcinoma (1); prostate carcinoma (1); punctate palmoplantar keratoderma type 1 (1); RASopathies (1); retinal detachment (1); tuberculosis (1); uveal melanoma (1); Wilms tumor (1).